PGF (placental growth factor)
Diseases named in the same sentence as PGF in open-access papers (continued):
Sharing a sentence is not in itself a finding about the gene and the disease.
cancer (147 papers, 2005 to 2025). A tumor composed of atypical neoplastic, often pleomorphic cells that invade other tissues. "For reference, PGF is commonly used to refer to the gene encoding placental growth factor, but in the context of developing anti-cancer drugs targeting this specific protein, it is more appropriate to use the term PGF when referring to the expressed protein." (PMID 37508400, 2023). "Herein, we reveal that chemotherapy upregulates placental growth factor (PlGF), which directly activates cancer-associated fibroblasts (CAFs) to induce fibrosis-associated collagen deposition in PDAC." (PMID 36272973, 2022). "VEGFA and PGF levels were inversely associated with these scores in most cancers." (PMID 37852616, 2023). "Among the 10 paracrine factors were both known and unknown cancer promoting stromal factors, the former including Placental Growth Factor (PGF) and Periostin (POSTN), while Pregnancy-Associated Plasma Protein A (PAPPA) was among the latter." (PMID 26020769, 2015). "The survival analysis showed that VEGFA and placental growth factor (PGF) were correlated with poor prognosis in many cancers, including kidney renal cell and liver hepatocellular carcinoma." (PMID 37852616, 2023). "Hypoxia in HSCs and cancer cells increases the expression of placental growth factor (PlGF), a VEGF family member." (PMID 36362726, 2022). "In this review, we summarize recent findings regarding the immunomodulatory effects and cancer progression of the angiogenic growth factor namely placental growth factor (PlGF) and address the biological complex effects of this cytokine." (PMID 31216652, 2019). "Similar to NRP-1, placental growth factor (PlGF) is a member of the VEGF family and known to mediate angiogenesis, with circulating PlGF shown to be a prognostic marker for cancer." (PMID 31106153, 2019). "For instance, serum levels of pregnancy hormones such as beta human chorionic gonadotropin (HCG), pregnancy associated protein A (PAP-A), placenta growth factor (PGF), and estrogen correlate well with cancer progression." (PMID 28469531, 2017). "Placental growth factor (PlGF), a proangiogenic member of vascular endothelial growth family, is active during pathological conditions like cancer, metastasis formation and hind limb ischemia and in wound healing." (PMID 28427198, 2017). "Vascular endothelial growth factor (VEGF) family, of structurally related molecules including VEGFA, VEGFB, VEGFC, VEGFD and placental growth factor (PLGF), is one of the most potent angiogenic factors expressed in various human cancers." (PMID 22615958, 2012). "For instance, PSG1 (Pregnancy specific beta-1-glycoprotein 1), an immunoglobulin highly expressed in several kinds of cancers, involves in the regulation of placental growth factor (PGF), TGF-β-mediated vascular endothelial growth factor (VEGF) and the activation and proliferation of T-cell." (PMID 41323395, 2025). "So far, anti-PGF targeting strategies have gained interest for new anti-cancer drug development." (PMID 37508400, 2023). "Further, three up-regulated genes, PRLR, NOX1, and PGF, also contributed to several hallmarks of cancer, mainly including insensitivity to antigrowth signals, self-sufficiency in growth signals, and evading apoptosis, indicating their potential roles in tumorigenesis." (PMID 35741849, 2022). "Moreover, substances such as CCL2, CCL28, CXCL8, CXCL12, Ang-2, VEGF, placental growth factor (PlGF), and adenosine secreted by cancer cells promote the recruitment of immunosuppressive cells, such as M2-TAMs, MDSCs, and Treg cells." (PMID 35759090, 2022). "Also, their effectiveness may be enhanced when PGF inhibitors are combined with other cancer therapies, such as radiation, chemotherapy, immunotherapy, or anti-angiogenic drugs." (PMID 37508400, 2023).
cancer (continued). "Cell‐cell signaling pattern between basal cancer cells (Ca), FPCS, and TPCS revealed that while Ca‐Ca and Ca‐FPC signaling mainly comprised PGF, TGFA, and VEGFA signaling, TPCS uniquely received BMP signals (BMP2/4 and GDF5) from Ca." (PMID 38582099, 2024). "The most potent angiogenic pathway in cancer is the VEGF signalling pathway, which is composed of five ligands (VEGF-A, -B, -C, -D and placental growth factor [PlGF]) and three receptors (VEGFR-1, -2 and -3)." (PMID 36300092, 2022). "Members of the VEGF family (VEGF-A, -B, -C, -D, and placenta growth factor, PGF) are produced by many types of cancer, being the expression of VEGF-A usually correlated with metastatic potential." (PMID 36479090, 2022). "According to the pro-tumorigenic phenotype of cancer infiltrating NK cells, they can secrete pro-angiogenic factors, such as VEGF, transforming growth factor-beta (TGF-β), IL-8, IL-10, placental growth factor (PlGF), Ang-1, and Ang-2." (PMID 36419156, 2022). "PIGF (placental growth factor), is a member of the VEGF family, which can bind VEGFR1 with high affinity, plays a key role in pathological angiogenesis, especially in cancer, cardiovascular, autoimmune and inflammatory diseases." (PMID 36119065, 2022). "Genes such are GSTA4, GSTO2, KLK3, PGF were down-regulated and E2F2, MMP9, PIM2, VEGFC are up-regulated in all cancer nodules." (PMID 34209090, 2021). "It was previously reported that cancer cells recruit BMDCs through secretion of soluble factors, including SDF-1, VEGF, MMP-9, placental growth factor (PIGF), IL-1 beta, and granulocyte macrophage colony stimulating factor (GM-CSF)." (PMID 26416452, 2015). "In some cancer cell lines, vascular endothelial growth factor (VEGF) is suppressed by treatment while in others, placental growth factor (PlGF) is suppressed." (PMID 22963500, 2012). "Placental growth factor (PLGF), a member of the VEGF subfamily, is involved in cancer progression." (PMID 37190188, 2023). "Through a human circRNA microarray assay and bioinformatics analyses, we first found that circALG1 was highly expressed in both cancer tissues and peripheral blood from patients with CRC and that this high circALG1 expression promoted CRC metastasis through the miR-342-5p/PGF signalling axis." (PMID 35305647, 2022). "Adult transgenic mice lacking the PGF gene showed a defective response to ischemia, wound healing, inflammation and cancer, despite the normal development of embryonic vasculature." (PMID 29050240, 2017). "Interestingly only secretion of the placental growth factor (PlGF) was increased on treatment by evofosfamide under hypoxia and only by the evofosfamide-responsive and not by the evofosfamide-resistant carcinoma cells." (PMID 28423594, 2017). "In addition, several of these genes have not previously been reported as methylated in any type of cancer (KCNK4, SEPT5, PENK, BMP4, TAL1, PGF, SMARCB1 (INI1), FRZB (SFRP3), IRAK3 and MCM2)." (PMID 19493342, 2009).
infection (13 papers, 2018 to 2024). The state of being infected such as from the introduction of a foreign agent such as serum, vaccine, antigenic substance or organism. "The top upregulated genes in KSHV lytic and mixed infection spots are predicted to encode proteins that regulate angiogenesis including ADAMTS9, KDR and PGF, endothelial cell development including KDR and STC1, and cell-substrate adhesion, SPRY4, ITGA1, ADAMTS9, KDR, MMP12." (PMID 39386738, 2024). "Some of these genes belong to the NF-kappa B (NF-κB) (PLAU, VCAM1, TNFRSF1A) and/or mitogen-activated protein kinase (MAPK) (TNFRSF1A and PGF) signaling pathways, indicating a differential regulation of the inflammatory response in lungs for both infection outcomes." (PMID 35003125, 2021).
cardiovascular disease (11 papers, 2012 to 2024). "This review focuses on a novel concept wherein the development of CKD-associated cardiovascular diseases is associated with noninfectious inflammation mediated by the signaling pathway of placental growth factor (PlGF) and its receptor, fms-like tyrosine kinase-1 (Flt-1)." (PMID 36430665, 2022). "The HIF-1 signaling pathway is closely related to hypoxia–ischemia in cardiovascular diseases, and we found four genes (FLT1, KDR, ANGPT2, and PGF) related to angiogenesis in the pathway." (PMID 36435742, 2022).
retinopathy (10 papers, 2013 to 2024). "Placental growth factor (PGF) as a member of the VEGF family is implicated in pathological angiogenesis, particularly retinal disorders." (PMID 32774120, 2020). "We recently performed gene expression analysis in a rodent T2DM model of retinopathy showing that growth factors like fibroblast growth factor 2 (FGF2) and placental growth factor (PGF) may be involved in the disease progression." (PMID 28575111, 2017).
PGF also shares sentences with these, for which no sentence is quoted: diabetes (41 papers); ischemia (14); placental abruption (13); medulloblastoma (10); lymph node metastasis (8); pneumonia (8); acute renal failure (7); non-small cell lung carcinoma (6); renal disease (6); Thrombocytopenia (6); acute myocardial infarction (5); Arthritis (5); autoimmune disease (5); metabolic syndrome (5); pregnancy (5); pulmonary edema (5); renal failure (5); anemia (4); angiosarcoma (4); diabetic kidney disease (4); hematoma (4); leukemia (4); myocardial ischemia (4); neovascular glaucoma (4); Alzheimer disease (3); Anxiety (3); bronchopulmonary dysplasia (3); Cirrhosis (3); endometriosis (3); hyperlipidemia (3).
A further 213 diseases each share a sentence with PGF in 3 papers or fewer.